POLR2A (RNA polymerase II subunit A)
Description:
Catalytic core component of RNA polymerase II (Pol II), a DNA-dependent RNA polymerase which synthesizes mRNA precursors and many functional non-coding RNAs using the four ribonucleoside triphosphates as substrates (By similarity). Pol II-mediated transcription cycle proceeds through transcription initiation, transcription elongation and transcription termination stages. During transcription initiation, Pol II pre-initiation complex (PIC) is recruited to DNA promoters, with focused-type promoters containing either the initiator (Inr) element, or the TATA-box found in cell-type specific genes and dispersed-type promoters that often contain hypomethylated CpG islands usually found in housekeeping genes. Once the polymerase has escaped from the promoter it enters the elongation phase during which RNA is actively polymerized, based on complementarity with the template DNA strand. Transcription termination involves the release of the RNA transcript and polymerase from the DNA (By similarity). Forms Pol II active center together with the second largest subunit POLR2B/RPB2. Appends one nucleotide at a time to the 3' end of the nascent RNA, with POLR2A/RPB1 most likely contributing a Mg(2+)- coordinating DxDGD motif, and POLR2B/RPB2 participating in the coordination of a second Mg(2+) ion and providing lysine residues believed to facilitate Watson-Crick base pairing between the incoming nucleotide and template base. Typically, Mg(2+) ions direct a 5' nucleoside triphosphate to form a phosphodiester bond with the 3' hydroxyl of the preceding nucleotide of the nascent RNA, with the elimination of pyrophosphate. The reversible pyrophosphorolysis can occur at high pyrophosphate concentrations (By similarity). Can proofread the nascent RNA transcript by means of a 3' -> 5' exonuclease activity. If a ribonucleotide is mis-incorporated, backtracks along the template DNA and cleaves the phosphodiester bond releasing the mis-incorporated 5'-ribonucleotide (By similarity). Through its unique C-terminal domain (CTD, 52 heptapeptide tandem repeats) serves as a platform for assembly of factors that regulate transcription initiation, elongation and termination. CTD phosphorylation on Ser-5 mediates Pol II promoter escape, whereas phosphorylation on Ser-2 is required for Pol II pause release during transcription elongation and further pre-mRNA processing. Additionally, the regulation of gene expression levels depends on the balance between methylation and acetylation levels of the CTD-lysines. Initiation or early elongation steps of transcription of growth-factor-induced immediate early genes are regulated by the acetylation status of the CTD. Methylation and dimethylation have a repressive effect on target genes expression. Cooperates with mRNA splicing machinery in co-transcriptional 5'-end capping and co-transcriptional splicing of pre-mRNA (By similarity). RNA-dependent RNA polymerase that catalyzes the extension of a non-coding RNA (ncRNA) at the 3'-end using the four ribonucleoside triphosphates as substrates. An internal ncRNA sequence near the 3'-end serves as a template in a single-round Pol II-mediated RNA polymerization reaction. May decrease the stability of ncRNAs that repress Pol II-mediated gene transcription. (Microbial infection) Acts as an RNA-dependent RNA polymerase when associated with small delta antigen of Hepatitis delta virus, acting both as a replicase and transcriptase for the viral RNA circular genome.
Synonyms: POLR2; POLRA; RPB1; NEDHIB; RPBh1; RPO2; RPOL2; RpIILS; hRPB220; hsRPB1
Target class: Enzyme; Transferase
Safety:
Unwanted effects reported when the protein is acted on. In parentheses: how it was acted on, where the effect was seen, and who reports it.
thrombocytopenia (source: ClinPGx)
Gene: Protein-coding gene on chromosome 17 (7,484,366 to 7,514,616, forward strand). Ensembl gene ENSG00000181222.
Subcellular location: Nucleus; Cytoplasm; Chromosome
Subcellular location (Human Protein Atlas): Nucleoplasm; Cytosol
Pathways (Reactome):
Disease: Abortive elongation of HIV-1 transcript in the absence of Tat; Dengue Virus-Host Interactions; Formation of HIV elongation complex in the absence of HIV Tat; Formation of HIV-1 elongation complex containing HIV-1 Tat; Formation of the HIV-1 Early Elongation Complex; HIV Transcription Initiation; HIV elongation arrest and recovery; Pausing and recovery of HIV elongation; Pausing and recovery of Tat-mediated HIV elongation; RNA Pol II CTD phosphorylation and interaction with CE during HIV infection; RNA Polymerase II HIV Promoter Escape; Signaling by FGFR2 IIIa TM; Tat-mediated HIV elongation arrest and recovery; Tat-mediated elongation of the HIV-1 transcript; Transcription of the HIV genome; Viral Messenger RNA Synthesis
Gene expression (Transcription): Formation of RNA Pol II elongation complex; Formation of the Early Elongation Complex; MicroRNA (miRNA) biogenesis; PIWI-interacting RNA (piRNA) biogenesis; RNA Pol II CTD phosphorylation and interaction with CE; RNA Polymerase II Pre-transcription Events; RNA Polymerase II Promoter Escape; RNA Polymerase II Transcription Elongation; RNA Polymerase II Transcription Initiation; RNA Polymerase II Transcription Initiation And Promoter Clearance; RNA Polymerase II Transcription Pre-Initiation And Promoter Opening; RNA polymerase II transcribes snRNA genes; Transcriptional regulation by small RNAs
Metabolism of RNA: Processing of Capped Intron-Containing Pre-mRNA; mRNA Capping; mRNA Polyadenylation; mRNA Splicing - Major Pathway; mRNA Splicing - Minor Pathway
DNA Repair: Dual incision in TC-NER; Formation of TC-NER Pre-Incision Complex; Gap-filling DNA repair synthesis and ligation in TC-NER; Transcription-Coupled Nucleotide Excision Repair (TC-NER)
Signal Transduction: Estrogen-dependent gene expression
and 3 more pathways
Genetic constraint (gnomAD): Loss-of-function variants: 24 observed, 167.49 expected, observed/expected ratio (o/e) 0.14, 90% interval 0.1 to 0.2. The upper end of that interval is the gene's LOEUF score, 0.2, which puts it in group 1 of 6, group 1 being the genes least tolerant of losing a copy. Missense variants: 1,278 observed, 2,550.9 expected, observed/expected ratio (o/e) 0.5, 90% interval 0.48 to 0.52. Synonymous variants: 1,141 observed, 990.64 expected, observed/expected ratio (o/e) 1.15, 90% interval 1.1 to 1.21.
Gene-disease validity (ClinGen):
ClinGen rates the evidence that POLR2A causes each of these diseases.
neurodevelopmental disorder with hypotonia and variable intellectual and behavioral abnormalities (autosomal dominant): Definitive. Neurodevelopmental disorder in which the cause of the disease is a variation in the POLR2A gene; it is characterized by early-onset hypotonia, delayed walking, poor speech, and impaired intellectual development.
Homologues: Orthologues: dog POLR2A (96% identical), macaque POLR2A (96% identical), mouse Polr2a (96% identical), pig POLR2A (96% identical), rat Polr2a (96% identical), chimpanzee POLR2A (95% identical), tropical clawed frog polr2a (94% identical), guinea pig POLR2A (92% identical), zebrafish polr2a (91% identical), Drosophila melanogaster Polr2A (71% identical), Caenorhabditis elegans ama-1 (66% identical). Paralogues in human: POLR3A (26% identical), POLR1A (21% identical).
Diseases named in the same sentence as POLR2A in open-access papers:
POLR2A is named in the same sentence as 101 diseases in open-access papers, as found by Europe PMC text mining. Sharing a sentence is not in itself a finding about the gene and the disease. The quoted sentences say what the papers report.
meningioma (40 papers, 2017 to 2025). A generally slow growing tumor attached to the dura mater. "In the cohort of only CDKN2A intact/wt meningiomas, all meningiomas with PIK3CA or POLR2A mutations were CDKN2Alow cases, whereas the only meningioma with an ARID1A mutation was CDKN2Ahigh." (PMID 37093270, 2023). "Meningiomas with mutations in POLR2A were exclusively benign with distinct meningothelial histology and were more likely to arise from the tuberculum sellae." (PMID 36686824, 2022). "AKT1, KLF4, SMO, or POLR2A mutations were significantly more frequent in meningiomas of skull-base lesions than in those of supra-tentorial lesions (p = 8.3 × 10–11)." (PMID 33772057, 2021). "POLR2A (RNA Polymerase II Subunit A) mutations in meningiomas have also been identified, being linked to a meningothelial histology and tuberculum sellae tumors." (PMID 34300316, 2021). "Apart from NF2 alterations in sporadic meningiomas, various oncogenic mutations in KLF4, SMO, TRAF7, PIK3CA, AKT1 and POLR2A are also found to be clinically actionable genetic events in meningiomas." (PMID 34722286, 2021). "POLR2A mutations predominately display meningothelial histology and are almost exclusively found in grade I meningiomas, occurring in 6% of grade I tumors." (PMID 33801089, 2021). "This study shows that the POLR2A mutation is a potentially suitable marker for meningiomas with poor prognoses, especially among WHO grade I skull-base meningiomas." (PMID 33772057, 2021). "Meningiomas with identified pathogenic variants in POLR2A are most commonly mutually exclusive, genomically stable, and associated with benign meningiomas in the midline skull base, in particular the region of the tuberculum sellae." (PMID 33262459, 2021). "In particular, AKT1, KLF4, SMO, or POLR2A mutations were significantly more frequent in meningiomas of paraxial mesodermal origin than in those of neural crest (p = 1.7 × 10–10) and dorsal mesodermal origin (p = 3.0 × 10–4)." (PMID 33772057, 2021). "A recent study reported the NGS genomic analysis of 775 meningiomas, showing the recurrent mutation of the POLR2A gene, which encodes the catalytic subunit of RNA polymerase II." (PMID 30279357, 2018). "We calculated the significance of association of the driver mutations (NF2, SMARCB1, TRAF7/PI3K, TRAF7/KLF4, POLR2A, Hedgehog) with atypical meningiomas." (PMID 28195122, 2017). "As an exception, one patient presented with a psammomatous meningioma with a POLR2A mutation, and another patient presented with an angiomatous meningioma with a KLF4 mutation, while yet another patient presented with an atypical meningioma with an AKT1 mutation." (PMID 33772057, 2021). "Notably, non-synonymous genetic variants of SMO and POLR2A were restricted to diploid meningiomas, whereas NF2 mutations were only found among tumors that showed -22/22q─ (with or without a complex karyotype)." (PMID 34868937, 2021). "Moreover, this study reports that the POLR2A mutation may serve as a potential marker for meningiomas with poor prognoses." (PMID 33772057, 2021). "Hence, the POLR2A mutation may be a potentially useful predictor of tumor recurrence in skull-base WHO grade I meningiomas." (PMID 33772057, 2021). "However, mutations in TRAF7 can be present in isolation, though often they can co-occur with KLF4, AKT1, or PIK3CA mutations, whereas mutations in SMO and POLR2A are usually mutually exclusive Interestingly, the meningiomas arising from SMO and AKT1-MTOR aberrations often arise in the skull base." (PMID 33194703, 2020). "In addition to the established association of meningioma with pathogenic aberrations in the tumour suppressor gene NF2, genomic analyses have identified genes including TRAF7, KLF4, AKT1, SMO, PIK3CA and POLR2A to possess recurrent mutations in low grade non-NF2 mutant meningioma." (PMID 33167358, 2020).
meningioma (continued). "Functionally, POLR2A mutations disrupted the expression of key meningeal identity genes (WNT6, ZIC1/ZIC4), defining a distinct and clinically unique meningioma subgroup." (PMID 41487511, 2025). "Typically, POLR2A is correlated with meningothelial histology, tumor location in the tuberculum sellae, and exclusive presence in grade 1 meningiomas." (PMID 35565385, 2022). "We comprehensively evaluated associations among tumor location, pathological diagnosis (histological type), and genetic alterations including AKT1, KLF4, SMO, POLR2A, and NF2 mutations and 22q deletion in 269 meningioma cases." (PMID 33772057, 2021). "From the embryological viewpoint, we found that the meningiomas harboring AKT1, SMO, KLF4, or POLR2A mutations were significantly associated with paraxial mesodermal origin." (PMID 33772057, 2021). "In turn, the frequency of non-synonymous genetic variants that affected individual genes in these three cytogenetic subgroups of meningiomas revealed different mutational profiles among them for the NF2, SMO, and POLR2A genes." (PMID 34868937, 2021). "POLR2A- mutant meningiomas are WHO grade 1, are more likely present with a meningothelial histology, and are commonly located in the anterior cranial skull base." (PMID 33346248, 2020). "Exclusive of TRAF7, AKT1, PIK3CA, KFL4, and SMO, mutations in POLR2A, which encodes DNA-directed RNA polymerase II subunit RPB1, are found in 6% of meningiomas." (PMID 31970090, 2019). "POLR2A-mutant meningiomas display dysregulation of key meningeal identity genes, such WNT6 and ZIC1/ZIC4." (PMID 30279357, 2018). "To date, the most common alterations in sporadic meningiomas are NF2 mutations or loss of 22q, with non-NF2 mutant meningiomas harboring mutations in in AKT1, TRAF7, KLF4, POLR2A and SMO16–18." (PMID 28775249, 2017). "Beyond chromosomal deletions, somatic POLR2A mutations have also been identified in a cohort of 775 meningioma patients lacking known driver alterations; recurrent mutations such as p.Gln403Lys or a deletion of the p.Leu438_His439 region were detected." (PMID 41487511, 2025). "POLR2A (RNA polymerase II polypeptide A) mutations were found more commonly in benign meningiomas without large-scale chromosomal alterations." (PMID 36840836, 2023). "Notably, only one meningioma with an SMO mutation had an anterior location; however, numerous tumors harboring KLF or POLR2A mutations had a central location." (PMID 33772057, 2021). "Mutations in POLR2A lead to dysregulation of key meningeal identity genes ranging from wingless-type MMTV integration site family, member 6 (WNT6) to alpha prolamins (ZIC1) and are found in approximately 6% of meningiomas." (PMID 33346248, 2020). "POLR2A-mutant meningiomas do not exhibit mutations in other meningeal driver genes, such as NFE2, TRAF7, KLF4, AKT1, or SMO." (PMID 30279357, 2018). "Meningiomas with these alterations carry a significantly higher risk of being atypical as compared with non-NF2 meningiomas, including TRAF7 (with PI3K or KLF4 alterations), Hedgehog or POLR2A mutant tumours." (PMID 28195122, 2017). "Overall, WHO grade 1 meningiomas harbored numerous and heterogeneous genetic variants, which most frequently affected the NF2 (47%) gene and to a less extent the PNMA6A (22%), TIGD1 (16%), SMO (13%), PTEN (13%), CREG2 (9%), EEF1A1 (6%), POLR2A (6%), ARID1B (3%), and FAIM3 (3%) genes." (PMID 34868937, 2021). "Repeated mutations of POLR2A were found in samples lacking known meningioma driver genes, suggesting that POLR2A may play a role in tumorigenesis." (PMID 34899822, 2021). "We first searched for known meningioma driver mutations in each sample, defining the distribution of benign versus atypical meningiomas in each of the molecular subgroups including NF2, TRAF7 (co-mutated with PI3K pathway or KLF4), Hedgehog and POLR2A mutant tumours." (PMID 28195122, 2017).
meningioma (continued). "TRAF7 (along with NF2 and PI3K) associated meningiomas are more aggressive and recur at a significantly higher rate than other molecular subgroups of meningiomas (KLF4, POLR2A, and SMARCB1)." (PMID 41372821, 2025). "Previous investigations have identified Wnt pathway activation across meningiomas with SSVs targeting TRAF7, KLF4, PIK3CA, POLR2A, the Hedgehog pathway, and even NF2 and SMARCB125." (PMID 39251601, 2024). "Molecular differences in meningiomas have different demographic characteristics, with NF2-mutant meningiomas being more common in males, while KLF4- and POLR2A-mutant meningiomas are more common in females." (PMID 39796693, 2024). "Molecular analysis revealed that there were 152 NF2 meningiomas (54.1%) and non-NF2 meningiomas: 45.9% (129 cases) including “AKT1”: 11.4% (32 cases), “KLF4”:5.7% (16 cases), “POLR2A”:16 cases (5.7%), “SMO”: 0.7% (2 cases), and others:22.1% (62 cases)." (PMID 35570314, 2022). "A recent study of 469 meningiomas suggested a 22x higher recurrence rate in aggressive subgroups (NF2, PI3K, HH, TRAF7) compared to others (KLF4, POLR2A, SMARCB1)." (PMID 35213082, 2022). "Overall, these results confirm the high frequency of genetic variants of the NF2 gene and to a less extent also of the PTEN, SMO, and POLR2A genes, in WHO grade 1 meningiomas." (PMID 34868937, 2021). "Another four genes (PNMA6A, TIGD1, PTEN, and SMO) were found to be altered in >10% of all WHO grade 1 meningiomas investigated, while the remaining CREG2, EEF1A1, and POLR2A genes were recurrently altered in a minority (<10%) of cases." (PMID 34868937, 2021). "Of note, other common pathological relevant genes of meningiomas, including AKT1 (n = 3; 8%), CDKN2A (n = 2; 5%), SMO (n = 0; 0%), SUFU (n = 0; 0%), POLR2A (n = 6; 16%), TRAF7 (n = 1; 3%), and SMARCB1 (n = 2; 5%), were detected as well." (PMID 34778063, 2021). "Additional common pathological relevant genes of meningiomas, including AKT1 (n = 3; 8%), CDKN2A (n = 2; 5%), SMO (n = 0; 0%), SUFU (n = 0; 0%), POLR2A (n = 6; 16%), TRAF7 (n = 1; 3%), and SMARCB1 (n = 2; 5%), were observed as well." (PMID 34778063, 2021). "CDKN2A deleted meningiomas did not harbour SMARCB1, AKT1, PIK3CA, SMO, POLR2A, or RB1 somatic mutations." (PMID 37093270, 2023). "Furthermore, several typical meningioma locations have distinct related genomic markers (e.g., anterior skull base: SMO, AKT1E17K, TRAF7; central skull base: AKT1, KLF4, TRAF7, POLR2A, Convexity: NF-2, LOH chromosome 22, BAP1)." (PMID 38017560, 2023). "Thus, according to this study, five different molecular subgroups of meningiomas: NF2/SMARCAB1, KLF4/TRAF7, PI3K/TRAF7, Hedgehog, and POLR2A." (PMID 30279357, 2018). "At the time of sequencing, our clinically validated targeted NGS panel did not include several well-known meningioma driver genes (TRAF7, KLF4, or POLR2A), which is a limitation to this study." (PMID 36845294, 2023).